IL6 (interleukin 6)
Diseases named in the same sentence as IL6 in open-access papers (continued):
Sharing a sentence is not in itself a finding about the gene and the disease.
COVID-19 (continued). "The risk of severe infection in patients with diabetes and COVID-19 is associated with an increase in angiotensin-converting enzyme 2 (ACE 2), impaired T Cell function, and increased interleukin-6 (IL-6), which promotes COVID-19 infection due to increased viral entry and an impaired immune response." (PMID 40136608, 2025). "A key player in this process is interleukin-6 (IL-6), a pro-inflammatory cytokine and targeting this key player and treatment of the cytokine storm are important components for rescuing patients with severe COVID-19." (PMID 40410684, 2025). "The physiological factors that may mitigate COVID-19 in CF patients could be the localized respiratory tract reduction of IL-6, thick secretions in the respiratory tract, existing microbiota, and elevated autophagy induction." (PMID 40733537, 2025). "The relative gene expressions of IL-17 and VEGF-A were highly variable in post-COVID-19 patients, but the expressions of IL-6 and IL-12 showed a trend of being upregulated, while the expression of MIP-1A remained at basal levels in 9 out of 23 patients evaluated." (PMID 40508959, 2025). "Also, these findings support the efficacy of an IL-6 inhibitor (Actemra) and suggest the urgent need to block IL-17/IL-17R signaling to relieve the cytokine storm in critical cases of COVID-19." (PMID 41184328, 2025). "Tocilizumab, by inhibiting IL-6, enhances the immune response in COVID-19 patients." (PMID 40355215, 2025). "Regarding the immunohistochemical analysis, there was a statistically significant difference in the expression of the following markers, with higher concentrations in control group B compared to COVID-19 group A: IL-6 (p < 0.0001), IL-18 (p = 0.002), CASP-9 (p < 0.0001), and HIF (p = 0.0327)." (PMID 40004007, 2025). "In summary, we speculate that SG can regulate the NF-κB signaling pathway, inhibit the release of pro-inflammatory factors such as IL-6, and slow down the occurrence of a cytokine storm, thereby exerting a therapeutic effect on COVID-19." (PMID 40872607, 2025). "CRP, a nonspecific but reliable marker of inflammation, was elevated by an average of nearly 20 mg/L in co-infected patients (87.4 vs. 68.9 mg/L, p < 0.001), while IL-6, a critical cytokine in COVID-19 pathophysiology, was also notably higher (62.1 vs. 48.7 pg/mL, p < 0.001)." (PMID 39857695, 2025). "Furthermore, increased expression of IFN signaling pathway molecules along with IL-6 in long COVID-19 patients indicated a potential role of IFN signaling in the prolonged effects in these patients." (PMID 40055791, 2025). "Interestingly, our study also identified interleukin-6 as a central hub within the lung and brain tissues of deceased COVID-19 patients and was upregulated in the latter tissue but unexpectedly downregulated in the former." (PMID 41141600, 2025). "In addition, the cytokine storms observed in severe COVID-19, characterized by elevated levels of interleukin-6 (IL-6) and tumor necrosis factor-alpha (TNF-α), directly stimulate VEGF-A secretion from activated endothelial and immune cells." (PMID 40075026, 2025). "Future studies with appropriate controls, serial inflammatory and coagulation biomarkers (e.g., IL-6, CRP, D-dimer), and vessel-wall imaging could better delineate whether a subset of SAH during COVID-19 reflects causal biology versus coincidence." (PMID 41458771, 2025). "We now showed that IL-6 was positively correlated with clinical outcome regardless of vaccination status, suggesting that anti-inflammatory therapy is important even for vaccinated COVID-19 patients." (PMID 40868247, 2025). "The underlying mechanisms may involve that IL-6 and TNF-α drive cytokine storms in severe COVID-19 and are elevated during active SLE phases, causing tissue damage in both lupus and viral infections." (PMID 40643149, 2025).
COVID-19 (continued). "It has been reported that patients with T2DM and COVID-19 have elevated levels of proinflammatory cytokines, such as IL-6 and TNF-α, as well as higher white blood cell counts (such as neutrophils), suggesting a heightened inflammatory response compared to patients without T2DM." (PMID 41009326, 2025). "Taken together, this suggests that COVID-19 may work synergistically with the molecular changes already present in aging to further increase IL-6 levels, which serves to propagate the morbidity and mortality of the virus." (PMID 40333142, 2025). "When contextualised against the 2025 ELSO quarterly report (n = 6 142 VV-ECMO runs, 38% COVID-19), our cohort exhibited comparable 28-day survival (39% vs. 41%) yet a shorter median IL-6 half-life (31 h vs. 46 h), possibly reflecting the routine use of high-cut-off filters in our centres." (PMID 40565970, 2025). "Likewise, IL-6 has been validated as a potent prognostic biomarker for mortality in critically ill COVID-19 patients, while cardiac troponin elevations correlate strongly with fatal outcomes." (PMID 41303223, 2025). "Also, in PLWH/COVID-19, serum levels of a different set of interleukins (IL-5, IL-6, IL-9, and IL-15) and chemokine CXCL10 were upregulated." (PMID 41516165, 2025). "In this study, we evaluated the clinical efficacy of hemoadsorption using Efferon CT in an expanded cohort of patients with severe COVID-19 course resistant to anti-IL-6 therapies and required post-therapy MLV versus a matched control group with no hemoadsorption." (PMID 40115785, 2025). "Similarly, In China, elevated serum IL-6 levels have been documented in patients who died of COVID-19 compared to surviving cases." (PMID 38601541, 2024). "FDA-approved TNFα and IL-6 inhibitors have shown clinical promise in COVID-19 treatments." (PMID 38251382, 2024). "Of note, activation of the kynurenine pathway in individuals with COVID-19 correlates with high IL-6 levels and, by blunting the immune response, may facilitate SARS-CoV-2 infection and the development of severe disease." (PMID 37934800, 2024). "Importantly, elucidation of putative serum mediators revealed a significant upregulation of key cytokines in COVID-19 positive patients compared to controls, including IL-6, TNF-α, IL-1β, IL-10, and CRP." (PMID 38041432, 2024). "A case series study performed in the United States of America investigating whether IL-6 inhibitors could be beneficial as a treatment option for PLWH admitted to the hospital with COVID-19 found that there were multiple reports of secondary infections." (PMID 39597537, 2024). "Though medium dose dexamethasone, IL6 antagonist such as tocilizumab, JAK kinase inhibitor such as baricitinib are recommended to reduce the inflammatory damage for severe COVID-19, their broad spectrum of immunosuppression also predispose patients to other infections." (PMID 38459021, 2024). "Several laboratory markers from previous studies, such as increased D-dimer, decreased platelet count, decreased hemoglobin concentration, increased creatinine, increased Interleukin-6 (IL-6), and elevated cardiac troponin-I have become predictors of COVID-19 mortality." (PMID 38216918, 2024). "This elevated risk is evident even after adjusting for the therapeutic interventions for COVID-19, such as systemic steroids and IL-6 inhibitors, and after accounting for the use of invasive procedures like central lines, mechanical ventilation, and ECMO using propensity score matching." (PMID 39346658, 2024). "Therefore, IL-6 plays an important role in the pathogenesis of VTE in COVID-19 patients, its excessive signal transduction can promote the development of the coagulation cascade and VTE." (PMID 38493138, 2024). "Interestingly, FFAR2 appears to play a role in regulating probiotic activity, which has been shown to reduce IL-6 levels in COVID-19 patients." (PMID 38932276, 2024). "COVID-19 patients displayed elevated levels of IL-1β, IL-6, and TNF." (PMID 38392902, 2024).
COVID-19 (continued). "Although previous studies have linked IP-10 to the development of severe COVID-19, its role in early warning of disease development has not been fully explored, in contrast to cytokines such as IL-6 and TNF-α, which have been widely studied." (PMID 38710800, 2024). "In our study, serum IL-6 correlates with the severity of COVID-19, as previously shown by others." (PMID 39882243, 2024). "Therefore, the aim of the current study was to investigate the association between the IL-6 rs1800796, IL-10 rs1800896, TNF-α rs1800629, and IFITM3 rs12252 polymorphisms and the presence of post-COVID symptoms in previously hospitalized COVID-19 survivors." (PMID 38400050, 2024). "Correlation analysis between IL-6 serum levels and the distribution of all DC subtypes further showed that in COVID-19 patients, IL-6 was negatively relatedto the circulating absolute levels of the CD1c+ cDC2 subpopulation (r = −0.29, p = 0.034) and CD303+ pDC subsets (r = −0.29, p = 0.036)." (PMID 38731010, 2024). "EVs released from airway cells in PwCF may block IL-6-induced synthesis of acute phase proteins, resulting in less inflammation and less severe COVID-19." (PMID 38612524, 2024). "Several factors can influence the levels of inflammatory parameters, including the hyperinflammatory response, the virulence of microbial agents, COVID-19-induced immunosuppression, the administration of corticosteroids, IL-6 inhibitors such as tocilizumab, etc.." (PMID 38391578, 2024). "Intriguingly, IL-6 acts through a NF-κB positive feedback loop mediated by the NF-κB pathway and plays an important role in amplifying the inflammatory response in a mechanism study of COVID-19-induced cytokine storm." (PMID 39057037, 2024). "Additionally, IL-6 levels correlated with features of eGC impairment and predicted outcomes in an external COVID-19 cohort." (PMID 38598083, 2024). "It is known that patients with COVID-19 have elevated levels of IL-6." (PMID 39457048, 2024). "In addition, triglycerides, were also found to be upregulated in COVID-19 patients and it positively correlates with pro-inflammatory markers such as interleukin-6 (IL-6) and C-reactive protein (CRP)." (PMID 38799469, 2024). "For example, the upregulation of TNF-α and IL-6, two major cytokines in COVID-19, directly affects brain physiology and may negatively promote stress-related responses such as mood alterations." (PMID 39205157, 2024). "Therefore, close monitoring of changes in IL-6 and ferritin concentrations is of great value in assisting clinicans to rapidly identify thrombotic complications among COVID-19 patients, hence facilitating the timely effective managment." (PMID 38493138, 2024). "In a study, it was found that CX3CL1, D-dimer, procalcitonin, and Interleukin-6 could effectively predict mortality in patients with severe COVID-19." (PMID 38611597, 2024). "Additionally, there was increased secretion of several EC-derived inflammatory molecules previously identified in COVID-19 patients, including IL-1β, IL-6, and sICAM-1." (PMID 38576426, 2024). "Stratified by AARC score, the IL-6 levels were significantly elevated in the ACLF+COVID-19 patients with an AARC score grade I (80.12 [81.29-82.45] vs 11.15 [13.22-15.28]; p=0.018) and II (230.44 [81.87-495.25] vs 36.84 [12.85-81.01]; p=0.001) compared with the ACLF group." (PMID 39867341, 2024). "The cellular expression level of IL-6 in individuals older than 60 years with COVID-19 could have a potential predictive value for death, according to our findings." (PMID 38601541, 2024). "Notably, the cytokine storm resulting from hyperinflammation in COVID-19 patients, characterized by markedly elevated levels of pro-inflammatory cytokines such as IL1, IL6, and TNFa, has been linked to an increased risk of suicide." (PMID 38338174, 2024). "We also observed an increase in IL-6 in the appendixes of children with COVID-19, which may lead to a decrease in viral lytic activity." (PMID 38397914, 2024).
COVID-19 (continued). "Moreover, the number of teeth with periapical lesions was also correlated with the levels of blood biomarkers associated with COVID-19 severity such as WBC, HbA1c, and IL-6." (PMID 38246829, 2024). "We focused on S protein capacity for modulating the production of two COVID-19-relevant, pro-inflammatory cytokines such as Interleukin-6 (IL-6) and Interferon-γ (IFN-γ) in both primary and secondary immune responses, including those to polyclonal, mitogenic activators." (PMID 38675840, 2024). "In addition to inhibition of the TNFα, IL-1β and IL-6 induced NF-κB activation, several COVID-19 drugs inhibit the NF-κB activation through disrupting the crosstalk signaling, such as MAPK(JNK/ERK/p38), ANG II-AT1R and ACE2-MAS signaling pathways." (PMID 37872376, 2024). "High IL-6 levels have been found in COVID-19 patients, which may aid clinicians in the identification of at-risk patients for severe disease." (PMID 38251210, 2024). "Importantly, IL-8, a major mediator of systemic and pulmonary inflammatory response and a putative biomarker, along with IL-6, for COVID-19 severity, was significantly downregulated in zanubrutinib-treated patients." (PMID 39906744, 2024). "As for anti-IL6 strategies, their efficacy in improving the principal outcomes of COVID-19 continues to be controversial according to an updated Cochrane systematic review, in spite of the amount of available data, while the use of other immunosuppressants cannot be recommended at this time." (PMID 39274454, 2024). "Given the significance of these biomarkers in the clinical management of COVID-19, this study aimed to evaluate the effects of B. coagulans Unique IS-2 and B. clausii UBBC-07 on the levels of CRP, serum ferritin, LDH, D-dimer, and IL-6 in COVID-19 patients and on recovery." (PMID 39866999, 2024). "Also, the data indicated a strong correlation between IL-6 levels and reduced lymphocyte percentage in COVID-19 patients, which supports findings from other studies highlighting IL-6’s role in driving immune dysregulation." (PMID 39407725, 2024). "Our results indicate that younger age, lower IL-6 levels, receiving three or more doses of the COVID-19 vaccine, and having no comorbidities are associated with a higher probability of having serum IgG levels ≥ 21.08 g/L." (PMID 39717543, 2024). "In addition to other pro-inflammatory cytokines, such as Tumor necrosis factor α (TNFα) and IL6, IL1β is also related to COVID-19 pathogenesis." (PMID 39346556, 2024). "The analyses showed that COVID-19 patients with cardiovascular co-morbidities who also consumed statins had significantly lower plasma levels of IL-6 (adjusted p = 0.027), TNFα (adjusted p = 0.036), and IL-10 (adjusted p = 0.025) compared to COVID-19 patients with no CVD co-morbidities." (PMID 39518552, 2024). "Furthermore, IL-6 and sIL-6R serum levels were significantly inversely correlated in acute severe COVID-19 patients (r=-0.44, p<0.05)." (PMID 39835136, 2024). "Moreover, IL-6 had the highest prognostic value for prediction of clinical endpoint in COVID-19 patients." (PMID 39497823, 2024). "Similarly, two FDA-approved IL-6 inhibitor drugs (siltuximab and clazakizumab) have demonstrated promising results in treating COVID-19 patients, which have been described in the NIH COVID-19 Treatment Guidelines." (PMID 38251382, 2024). "In this study, our objective was to document our practical observations regarding the alignment of the ELISA and ECLIA methods in detecting serum IL-6 levels during the initial surge of the COVID-19 pandemic in Italy, conducted at Careggi University Hospital in Florence (Italy)." (PMID 38617587, 2024). "Furthermore, it was the first study to measure serum miR374b-5p and found a lower level of miR374b-5p, while we found a significant increase in IL6 in the blood of COVID-19 patients compared to controls." (PMID 39729489, 2024).
COVID-19 (continued). "EVs could activate neutrophils, which might also trigger the release of serine proteases, which are believed to result in less severe COVID-19 by breaking down IL-6." (PMID 38612524, 2024). "The fourth is pathway is through cytokine storm: in COVID-19, the cytokine storm is characterised by an excessive production of pro-inflammatory cytokines such as IL-6, IL-1, IL-18, and granulocyte-macrophage colony-stimulating factor (GM-CSF), particularly in severe instances." (PMID 38214889, 2024). "Serum levels of interleukin-6 (IL-6) are increased in COVID-19 patients." (PMID 39835136, 2024). "Exposure to CS or nicotine upregulated many genes within AGE-RAGE signalling with high confidence, including CCND1, CXCL8, HRAS, IL6, KRAS and TNF, suggesting that smokers have a hyperactive AGE-RAGE and are therefore more at risk of severe COVID-19." (PMID 38991709, 2024). "Fold change of NEAT1, miR374b-5p, and IL-6 levels in COVID-19 and healthy controls." (PMID 39729489, 2024). "The level of IL-6 decreased in COVID-19 patient plasma during dexamethasone treatment." (PMID 39640429, 2024). "Interleukin 6 (IL-6) is one of the most widely recognised cytokine markers of inflammation, providing clinicians with valuable information for the early identification of patients with severe COVID-19 during the course of the disease." (PMID 38783290, 2024). "With regard to the AUC-ROC analysis, parameters such as SpO2, CRP, ALT, AST, and D-dimer levels exhibited good discriminatory power between co-infected and COVID-19 patients alone, while others like IL-6 and lymphocyte count showed higher sensitivity but lower specificity." (PMID 38793006, 2024). "It has been seen that severe COVID-19 is characterized by higher levels of some inflammatory biomarkers such as C-reactive protein (CRP), erythrocyte sedimentation rate (ESR), procalcitonin (PCT), and interleukin 6 (IL-6) when compared with mild-to-moderate COVID-19." (PMID 39204242, 2024). "Severe patients with COVID-19 more frequently had increased inflammatory monocytes and neutrophils and a sharp decrease in lymphocytes, with higher levels of IL-1β, IL-6, and TNF-α, leading to systemic organ failure and tissue damage." (PMID 39777148, 2024). "Besides, positive associations between serum transgelin with interleukin-6 (IL-6), CRP, D-Dimer, and lactate dehydrogenase (LDH) were observed among COVID-19 patients." (PMID 39676863, 2024). "Indeed, we and others previously found that COVID-19 patients with neurological complications had elevated serum immune mediators and cytokines (IL-6, IL-12p40, IL1-RA, M-CSF, CCL2, and HGF) which correlated with serum brain injury markers." (PMID 39474424, 2024). "Accordingly, a serial evaluation of IL-6 levels might be helpful in predicting COVID-19 pathogenesis." (PMID 39062668, 2024). "The dual role of IL-6, both as an indicator of tumor-related inflammation and a predictor of COVID-19 adverse outcomes, suggests that targeting the IL-6 pathway might offer therapeutic benefits in this patient population." (PMID 39272832, 2024). "Interestingly, IL-6 has been proposed as the most frequent cytokine released in severe forms of COVID-19." (PMID 40303184, 2024). "EVs released by cells in PwCF contain proteins that may impact neutrophil recruitment and activation, potentially resulting in less severe COVID-19 by inhibiting IL-6-induced acute phase mediators." (PMID 38612524, 2024). "To investigate whether lymphocyte depletion in patients with severe COVID-19 is associated with cytokine levels, we correlated lymphocyte levels in patients with severe COVID-19 with their IL6, IFN γ, and TNF-α levels." (PMID 39407725, 2024). "Dexamethasone can inhibit the expression of cytokines in COVID-19 patient including IL-6." (PMID 39640429, 2024).